HPX (hemopexin)
Diseases named in the same sentence as HPX in open-access papers (continued):
Sharing a sentence is not in itself a finding about the gene and the disease.
colitis (2 papers, 2019 to 2025). Inflammation of the colon. "Here we investigate the protective role of IL-22 and hemopexin in the context of colitis using the dextran sodium sulphate (DSS) acute colitis model in mice." (PMID 40791589, 2025). "Together, these results show that exogenous hemopexin has a protective effect in acute colitis and further indicate that hemopexin induction during colitis is dependent on IL-22ra1 signaling." (PMID 40791589, 2025). "Of note, alpha-1-B glycoprotein (A1BG) was also decreased, whereas haptoglobin (HP), pregnancy zone protein (PZP), and hemopexin (HPX) were increased throughout the colitis progression in IL-10−/− mice." (PMID 30774653, 2019). "IL-22 signaling was crucial for the induction of hemopexin in the colon, as Il22ra1-/- mice exhibited limited hemopexin induction and more severe colitis, which could be reversed by recombinant hemopexin administration." (PMID 40791589, 2025). "Despite similar body weights between PBS-treated (control) and hemopexin-treated Il22ra1-/- mice during the experiment, colitis severity was significantly attenuated by exogenous hemopexin treatment as indicated by lower DAI scores and improved colonic lengths when compared to PBS treatment." (PMID 40791589, 2025). "This was evidenced by the limited hemopexin induction in the liver and its reduced presence in the serum and feces of Il-22ra1-/- mice and by the consequent severity of DSS-induced colitis, which could be reversed by recombinant hemopexin treatment." (PMID 40791589, 2025). "Given the role of IL-22 in epithelial protection and tissue homeostasis, along with the growing recognition of the influence of the gut microbiota in IBD, we hypothesize that IL-22 signaling may drive hemopexin upregulation as a protective mechanism in colitis." (PMID 40791589, 2025).
coronary atherosclerosis (2 papers, 2020 to 2021). Atherosclerosis of the coronary vasculature. "But in an earlier study, an increase in the content of transthyretin, hemopexin and retinol-binding protein-4 was found in blood serum samples of patients with verified coronary atherosclerosis." (PMID 34948066, 2021). "Proteome profiling of serum revealed a change in the content of kininogen, hemopexin, transthyretin, retinol-binding protein, and proteins of the complement system (C9, and C3) in coronary atherosclerosis." (PMID 33033454, 2020).
coronary heart disease (2 papers, 2023 to 2024). "Quantitative proteomics analysis revealed that the serum concentration of hemopexin was elevated in individuals with coronary heart disease (CHD) and coronary atherosclerosis compared to healthy controls." (PMID 38022615, 2023). "Moreover, due to myocardial ischemia and hypoxia, patients with coronary heart disease require enhanced transport and utilization efficiency of oxygen in the blood, and hemopexin and tetrapyrrole binding proteins may play an important role in this process." (PMID 39470548, 2024).
dengue (2 papers, 2015 to 2023). "HPX levels were 10% of controls in severe dengue associated with hemorrhagic fever (DHF) and a rapid drop in platelets, during a dengue epidemic in Thailand." (PMID 26175690, 2015). "Besides, a 2014 study revealed increased levels of HPX and vitronectin in both DF and DHF compared to healthy controls, suggesting HPX as a potential biomarker to distinguish between uncomplicated dengue fever and dengue hemorrhagic fever." (PMID 38022615, 2023). "In DHF, fibronectin, HPX, and transferrin levels significantly rise in all three phases compared to Dengue Fever (DF)." (PMID 38022615, 2023). "HPX levels may help determine the severity of the illness, discriminate between dengue hemorrhagic fever (DHF) and uncomplicated dengue fever (DF), which would aid in diagnosis and treatment; and fibronectin, HPX and transferrin were found to be significantly decreased in DHF." (PMID 26175690, 2015).
depression (2 papers, 2012 to 2023). "Elevated hemopexin levels have also been found in inflammatory psychiatric disorders, such as major depression, schizophrenia, and mania." (PMID 23039107, 2012).
fibrosis (2 papers, 2011 to 2016). the formation of excess fibrous connective tissue in an organ or tissue in a reparative or reactive process. "Mac-2-binding protein, alpha-2-macroglobulin and hemopexin levels were found increased while A-1-antitrypsin, leucine-rich alpha-2-glycoprotein and fetuin-A were decreased in advanced fibrosis F4 as compared to early fibrosis F0/F1." (PMID 21299910, 2011).
Hematuria (2 papers, 2019 to 2021). The presence of blood in the urine. "Envenomed rats presented hematuria, hemoglobin deposition inside proximal and distal tubules and heme-scavenging molecules (such as hemopexin, heme-oxygenase-1 and biliverdin-reductase) was found to be up-regulated in envenomed kidneys." (PMID 30763408, 2019).
Hypertension (2 papers, 2017 to 2020). The presence of chronic increased pressure in the systemic arterial system. "Therefore, our results suggest that the linear decrease in KLF2, HPX, TMEM8A, ADAMTS-8 and AP3S2 expression in the broiler kidney is directly or indirectly related to blood pressure, hypertension and weight gain." (PMID 28924246, 2017).
ischemia (2 papers, 2013 to 2020). A hypoperfusion of the BLOOD through an organ or tissue caused by a PATHOLOGIC CONSTRICTION or obstruction of its BLOOD VESSELS, or an absence of BLOOD CIRCULATION. "In the present study, we found that protein level of HPX in the ischemic penumbra was increased at 24h following ischemia-reperfusion injury as compared with the sham-operated group." (PMID 23758755, 2013). "In the present study, we designed experiments to determine the cellular location and expression level changes of HPX after focal ischemia and reperfusion injury, and subsequently explore the therapeutic effect of HPX using a rat model of middle cerebral artery occlusion (MCAO)." (PMID 23758755, 2013). "This is exemplified by the fact that low levels of HPX, with a mean concentration of 2.6 mg/l and a range of 1.8–3.4 mg/l in the cerebrospinal fluid would be insufficient to cope with the quantities of heme released during ischemia reperfusion." (PMID 23758755, 2013). "Hemopexin (HPX), another protein related to oxidative stress, was also upregulated after ischemia and CAC treatment." (PMID 32143690, 2020). "Many of them have been previously correlated with response to ischemia (MAP 4, HPX, S100A proteins) as well as with angiogenic- and revascularization-related processes (LCN2, LRG1, CD44, MAPKAPK2)." (PMID 32143690, 2020).
ischemia reperfusion injury (2 papers, 2013 to 2019). Adverse functional, metabolic, or structural changes in ischemic tissues resulting from the restoration of blood flow to the tissue (reperfusion), including swelling; hemorrhage; necrosis; and damage from free radicals. "Together, these evidences indicate that HPX might offer neuroprotective effects following ischemia-reperfusion injury." (PMID 23758755, 2013). "In summary, the ability of HPX to up-regulate HO-1 signaling and repair the vascular micro-environment may play an important role in the improved functional outcome observed in rats following ischemia-reperfusion injury." (PMID 30646866, 2019).
kidney damage (2 papers, 2020 to 2023). "In addition, these 106 potential classifiers/biomarkers between TCMR vs. STA are associated with kidney damage (e.g., ATP1B1, CST3, FAH, GSS, HPX and LYZ), tubule injury (e.g., CRYM, GSS, HAGH, HPX and LYZ) and kidney inflammation (e.g., DCN)." (PMID 36814924, 2023). "However, hemopexin has been shown to have toxic protease activity that can lead to kidney damage reflected in diabetic nephropathy." (PMID 32933222, 2020).
kidney inflammation (2 papers, 2023 to 2024). "In contrast, ALCAM and HPX are associated with nephritis and central nervous system (CNS) involvement." (PMID 38915417, 2024).
malnutrition (2 papers, 2020 to 2022). Inadequate nutrition resulting from poor diet, malabsorption, or abnormal nutrient distribution. "Serum transferrin and hemopexin often decline together during acute-phase reactions and malnutrition." (PMID 36430211, 2022). "Transferrin and hemopexin are involved in the transport and storage of iron, and they often decline together with albumin during acute-phase reactions and malnutrition." (PMID 32472529, 2020).
pancreatic ductal adenocarcinoma (2 papers, 2020 to 2025). An infiltrating adenocarcinoma that arises from the epithelial cells of the pancreas. "Our findings suggest that hemopexin is a lymph node metastasis-associated protein that could potentially serve as a useful therapeutic target or biomarker of pancreatic ductal adenocarcinoma." (PMID 32663208, 2020).
plague (2 papers, 2017 to 2019). Plague is a severe bacterial infection caused by the gram-negative bacterium Yersinia pestis. "An increase in transferrin and hemopexin is highly correlative with anti-microbial activity and protection against plague in mice immediately after attenuated Yersinia pasties vaccine administration, with protection involving biological activities of host iron and heme-binding proteins." (PMID 30778356, 2019).
Psychological distress (2 papers, 2018 to 2020). "There, we found hemopexin, complement factor B, and clusterin, among others, to be positively associated with increased psychological distress in CWP." (PMID 32719459, 2020). "By interpreting the score plot in combination with the loading plot for HADSCWP, three of the proteins with highest VIP value were positively associated with psychological distress: complement factor B, complement C1r subcomponent, and hemopexin." (PMID 30555396, 2018). "Psychological distress in CWP was associated with plasma proteins related to immunity response and iron ion metabolism such as complement factor B, complement C1r subcomponent, and hemopexin." (PMID 30555396, 2018).
thalassemia (2 papers, 2012 to 2013). An inherited blood disorder characterized by a decreased synthesis of one of the polypeptide chains that form hemoglobin. "Indeed, low levels of hemopexin are found in SCD and thalassemia, whereas levels of heme are high in the plasma of Plasmodium-infected mice." (PMID 23358441, 2013).
acute coronary syndrome (1 paper, 2020). Signs and symptoms related to acute ischemia of the myocardium secondary to coronary artery disease. "Thus, in our preliminary studies, we have identified 10 distinct altered phosphoproteins from CAD plasma, among which Apo-A1, hemopexin, haptoglobin, and Alpha-antitrypsin have been reported to be associated with acute coronary syndrome." (PMID 33299376, 2020).
acute respiratory failure (1 paper, 2025). Life-threatening respiratory failure that develops rapidly. "In this study, we investigated the incidence of hemolysis, reflected by decreased haptoglobin and hemopexin levels, in septic patients with acute respiratory failure admitted to the ICU." (PMID 40429487, 2025).
aspergillosis (1 paper, 2025). Aspergillosis is an infection, growth, or allergic response caused by the Aspergillus fungus. "To determine the contribution of hemopexin to host defense in aspergillosis, we next infected neutropenic wild-type and hemopexin-deficient mice with Aspergillus conidia." (PMID 40232861, 2025). "Taken together, these data indicate that neutropenic hemopexin-deficient mice develop more severe aspergillosis than wild-type counterparts." (PMID 40232861, 2025). "To assess this feature of NETosis in aspergillosis, we compared the concentration of citrullinated histone-3 in the alveoli of hemopexin-deficient mice challenged with ΔCgrA germlings, with or without heme." (PMID 40232861, 2025). "We conclude that labile extracellular heme released from local hemolysis during aspergillosis is at the nexus of a series of pathogenic mechanisms, including enhancing fungal growth and, separately, inducing lung injury via NETosis, with hemopexin acting as a potent defense against these processes." (PMID 40232861, 2025). "To determine the contribution of heme and hemopexin to NET production during aspergillosis, we next compared BAL NET quantity in wild-type and hemopexin-deficient mice with invasive aspergillosis and found higher NET levels in hemopexin-deficient mice." (PMID 40232861, 2025). "Taken together, these data indicate that, independent of fungal growth, intra-alveolar extracellular heme during aspergillosis mediates lung injury, and hemopexin provides protection against this injury — consistent with the prediction of the computational model." (PMID 40232861, 2025). "To test whether plasma hemopexin scavenges extracellular heme in infected lungs, we measured plasma hemopexin concentration after intrapulmonary administration of exogenous heme to animals with experimental aspergillosis." (PMID 40232861, 2025). "To assimilate these interdependent processes, we hypothesized that, during aspergillosis, heme mediates direct lung injury independent of fungal growth, leading to worse infection outcomes, and the scavenger protein hemopexin mitigates these effects." (PMID 40232861, 2025).
autoimmune disease (1 paper, 2018). A disorder resulting from loss of function or tissue destruction of an organ or multiple organs, arising from humoral or cellular immune responses of the individual to their own tissue constituents. "In the context of autoimmune disease, HPX plays an important role in mercury-induced autoimmunity." (PMID 29323127, 2018).
babesiosis (1 paper, 2014). Babesiosis refers to a condition caused by microscopic parasites that infect the red blood cells. "Three APP involved in haemoglobin and iron metabolism and transport, haptoglobin, hemopexin and serotransferrin, indicate the role of haemolysis in the course of babesiosis." (PMID 24885808, 2014). "The role of haemolysis in the course of babesiosis was demonstrated by haptoglobin, hemopexin and serotransferrin expression changes." (PMID 24885808, 2014).
cervical cancer (1 paper, 2023). A primary or metastatic malignant neoplasm involving the cervix. "Six interesting core DEPs (SPARC, HPX, VCAM1, TFRC, ERN1 and APMAP) were confirmed to be potential plasma diagnostic markers for LVSI and LNM in cervical cancer patients." (PMID 37689639, 2023).
chronic fatigue syndrome (1 paper, 2023). "In addition, both HPX and PEDF were among 20 proteins in the CSF that were associated with Persian Gulf War Illness in soldiers, an equivalent to chronic fatigue syndrome." (PMID 37365509, 2023).
chronic hepatitis (1 paper, 2013). An active inflammatory process affecting the liver for more than six months. "A study, which measured levels of fucosylated HPX found significantly, elevated quantities of its expression in a cohort of 229 serum samples from patients with chronic hepatitis, LC, and HCC; a finding that was previously reported in an earlier publication." (PMID 23935864, 2013). "A recent study by Japanese investigators also assessing the clinical utility of serum fucosylated hemopexin in HCC, LC and chronic hepatitis subjects concluded that the glycoprotein could be used as a biomarker potentially indicative of a hypercarcinogenic liver." (PMID 23935864, 2013).
co-infection (1 paper, 2021). "We investigated serum HPX levels and found that single infection or co-infection with P. chabaudi and/or C. rodentium led to robust HPX secretion." (PMID 33440153, 2021). "However, we found that either single P. chabaudi infection or co-infection with C. rodentium induced robust HPX secretion, indicating that this protective axis was intact." (PMID 33440153, 2021).
cyst (1 paper, 2017). A sac-like closed membranous structure that may be empty or contain fluid or amorphous material. "Another example were LDL and hemopexin, which were found in the cyst’s tissue but were scarce in the vesicular fluid." (PMID 28945737, 2017).
diabetic macular edema (1 paper, 2022). "Overexpression of HPX has been reported in the vitreous fluid of diabetic macular edema patients by proteomic analysis, probably due to leakage from the BRB." (PMID 35742911, 2022).
diabetic retinopathy (1 paper, 2016). "The finding of high level of hemopexin in the saliva of PDR patients supported the hypothesis that hyperglycemia, changes in the redox homeostasis and oxidative stress are key pathogenic events in diabetic retinopathy." (PMID 27280065, 2016).
endothelial dysfunction (1 paper, 2024). In vascular diseases, endothelial dysfunction is a systemic pathological state of the endothelium (the inner lining of blood vessels) and can be broadly defined as an imbalance between vasodilating and vasoconstricting substances produced by (or acting on) the endothelium. "Additionally, LDL fraction contained higher concentrations of heme unlike HDL which contained more hemopexin suggesting an important role of HDL fraction in the defense against heme induced endothelial dysfunction." (PMID 38755670, 2024).
endotoxemia (1 paper, 2021). "The inflammatory cytokines TNF-α, interleukin-1ß (IL1ß) and interleukin-6 (IL6) were strikingly increased in LPS- and HpX-treated animals as compared to untreated controls indicating peripheral inflammation caused by endotoxemia or surgical treatment." (PMID 32557202, 2021).
experimental autoimmune encephalomyelitis (1 paper, 2018). An autoimmune demyelinating disease of the central nervous system that is produced experimentally in animals by the injection of homogenized brain or spinal cord in Freund's adjuvant. "In addition, the depletion of HPX levels implicated in a number of inflammatory diseases such as septic shock and experimental autoimmune encephalomyelitis." (PMID 29761050, 2018).
fibromyalgia (1 paper, 2025). A chronic disorder of unknown etiology characterized by pain, stiffness, and tenderness in the muscles of neck, shoulders, back, hips, arms, and legs. "Multiple proteoforms of hemopexin, primarily resulting from oxidation, differential glycosylation, and limited proteolysis, have been identified in different conditions, including fibromyalgia." (PMID 40700276, 2025).
gastric disease (1 paper, 2023). "APOA1BP, PGC, HPX, and DDT were discovered to be connected to the risk of gastric disease progression and to be able to forecast the progression of gastric disease in a prospective study on proteomic analysis, GPL, and early gastric cancer." (PMID 37719006, 2023).
Granuloma (1 paper, 2017). A compact, organized collection of mature mononuclear phagocytes, which may be but is not necessarily accompanied by accessory features such as necrosis. "In contrast, the necrotic center of a caseous granuloma showed accumulation of transferrin (TF), haptoglobin (HP), and hemopexin (HPX), which are potent extracellular sequesterers of Fe3+, Hb, and heme, respectively." (PMID 28811344, 2017).
hair disorder (1 paper, 2018). "However, the role of HPX in hair disorder had not been studied previously." (PMID 29323127, 2018).
hemolytic-uremic syndrome (1 paper, 2023). Acute kidney injury associated with microangiopathic hemolytic anemia and thrombocytopenia. "For instance, in a mouse model of Shiga toxin-induced hemolytic-uremic syndrome (HUS), HPX deficiency was protective in resolving HUS pathology." (PMID 38022615, 2023).